ATP7B (ATPase copper transporting beta)
Diseases named in the same sentence as ATP7B in open-access papers (continued):
Sharing a sentence is not in itself a finding about the gene and the disease.
breast carcinoma (16 papers, 2016 to 2025). "Decreased expression of the copper exporters ATPase copper transporting α (ATP7A) and ATPase copper transporting β (ATP7B) have been associated with decreased chemotherapy resistance in breast cancer cells." (PMID 37180167, 2023). "Higher expression level of CISD1 was found to be associated with worse clinical outcome (P = 4E-04, log-rank test), and high expression of ATP7B was significantly associated with long survival time of breast cancer patients (P = 0.0203, log-rank test)." (PMID 33281885, 2020). "ATP7B contributes to the development of breast cancer by participating in the cell cycle, oxidative phosphorylation, and DNA replication pathways." (PMID 39676279, 2024). "In the cohort study, high expression of LIAS, FDX1, LIPT1, DLD, PDH1, and ATP7B, coupled with low CDKN2A expression, was associated with favorable RFS in patients with estrogen receptor-positive early breast cancer (ER+ EBC)." (PMID 39867656, 2024). "ATP7B and DLAT are both mutated in breast cancer samples, with the most common mutation being missense mutation." (PMID 37180167, 2023). "In breast cancer samples, ATP7A (18%), amyloid beta precursor protein (APP) (11%) and ATP7B (9%) were the more frequently mutated genes." (PMID 37180167, 2023). "Since DLAT, SLC31A1, ATP7A and ATP7B were all found to be related to prognosis in breast cancer, a combined prognostic model aggregating more cuproptosis-related genes and clinical features is expected in future." (PMID 35996075, 2022). "We found that genes DLAT, SLC31A1, ATP7A and ATP7B were significantly related to the overall survival (OS) of breast cancer patients in univariate Cox regression analysis." (PMID 35996075, 2022). "Then, we investigated the roles of ATP7A and ATP7B in proliferation of breast cancer cells by transfecting ATP7A or ATP7B siRNAs into MDA‐MB‐231 and T47D cells, respectively." (PMID 32508020, 2020). "Research findings indicated that basal-like subtype patients exhibited reduced ATP7B expression, implying that copper concentrations in the tumor tissue of individuals with basal-like breast cancer may vary from those observed in other breast cancer subtypes." (PMID 41278297, 2025). "In particular, the molecular mechanism underlying the association between elevated ATP7B expression and breast cancer drug resistance has not been explored in detail, thereby limiting the mechanistic persuasiveness of the study." (PMID 41278297, 2025). "Although high expression of ATP7B has been reported to increase cisplatin resistance, its role in breast cancer (BC) remains unclear." (PMID 40316883, 2025). "High expression of ATP7A in breast cancer was significantly linked with reduced survival, while ATP7B showed no statistical difference." (PMID 39676279, 2024). "Furthermore, the expression levels of ATP7A and ATP7B in BRCA tissues were slightly higher than those in normal tissues, and the expression of ATP7A and ATP7B in different subtypes of breast cancer was also similar." (PMID 32508020, 2020). "Additionally, with adequate funding support gene knockdown experiments will be designed to investigate the influence of target genes, such as GSTM2 and ATP7B, on the biological behavior of breast cancer cells, thereby improving the functional depth and clinical relevance of the study." (PMID 41278297, 2025). "We identified 13 members of the copper transport system associated with the occurrence, progression, and mortality of breast cancer, including SLC31A1, DMT1, ATP7A, ATP7B, MTs, GSH, ATOX1, CCS, COX17, SCO1, SCO2, and COX11." (PMID 39676279, 2024). "ATOX1 regulates intracellular copper transport to key proteins such as ATP7A, ATP7B, and SOD1, while also promoting inflammatory neovascularization, wound healing, and the migration of breast cancer cells." (PMID 39867656, 2024). "HPAanalyze, a visualization R package, presented the expression of ATP7B and DLAT proteins in myoepithelial and glandular cells in breast cancer tissue using a heatmap." (PMID 37180167, 2023).
breast carcinoma (continued). "To reveal additional links to the biological function of ATP7B and DLAT in breast cancer development, we utilized the functional module of LinkedOmics to analyze genes that were positively or negatively correlated with ATP7B and DLAT." (PMID 37180167, 2023). "Specifically, we analyzed the protein expression, the related genes and the metabolic pathways of the essential copper-related genes, namely ATP7B and DLAT, in breast cancer samples." (PMID 37180167, 2023). "Immunohistochemistry staining showed high protein expression of ATP7B and DLAT in breast cancer samples." (PMID 37180167, 2023). "Two essential copper-related genes, ATP7B and DLAT, were selected to construct the scoring model to predict breast cancer patient survival." (PMID 37180167, 2023). "Consistent with the data from R language, starBase showed that expression levels of CDKN2A, SLC31A1, ATP7B, and PDHB were markedly up-regulated in breast cancer with respect to normal samples." (PMID 37884650, 2023). "Besides, we wonder what critical role ATP7B and DLAT played in breast cancer, given that these genes are essential for copper homeostasis and cuproptosis." (PMID 37180167, 2023). "Similarly, breast cancer is characterized by the overexpression of CTR1, ATP7B, ATOX1, and COX17." (PMID 41516324, 2025). "The expression of ATP7B and SLC31A1 were decreased and increased, respectively, in the basal-like subtype patients, suggesting that patients with the basal-like subtype of breast cancer may have different levels of copper in their tumor tissues compared with those with other breast cancer subtypes." (PMID 37180167, 2023). "Also ATP7B was found upregulated in breast cancer but not in normal adjacent tissue." (PMID 28425924, 2017). "Intriguingly, the expression of ATP7B and DLAT were decreased and increased respectively in the basal-like subtype compared with non-cancerous samples, which is opposite to those in other breast cancer subtypes." (PMID 37180167, 2023).
copper metabolism disorder (14 papers, 2013 to 2025). "Wilson’s disease (WD) is among the copper metabolism disorders primarily caused by mutations in the ATPase copper-transporting beta (ATP7B) gene." (PMID 39056796, 2024). "Due to the copper metabolism disorder caused by ATP7B mutation, most of the copper is deposited in the basal ganglia and cortex of the brain." (PMID 38660222, 2024). "Wilson’s disease (WD), a copper metabolism disorder, is primarily caused by mutations in the ATPase copper transporting beta (ATP7B) gene." (PMID 39056796, 2024). "As the primary pathological organ in HLD, pathological changes in the liver are caused by mutations in the ATP7B gene and copper metabolism disorder." (PMID 35401189, 2022). "Hepatolenticular degeneration (HLD) is an autosomal recessive copper metabolism disorder caused by mutations in the ATP7B gene." (PMID 34135753, 2021). "Wilson's disease (WD) is an autosomal recessive genetic disease caused by mutations in ATP7B and characterized by copper metabolism disorders." (PMID 30884209, 2019). "In addition, the total protein and RNA extracted from the rat liver tissues were examined, and the results showed that the expression of ATP7B and superoxide dismutase copper molecular chaperone CCS was significantly reduced after copper accumulation, suggesting a copper transport disorder." (PMID 34135753, 2021).
hepatocellular carcinoma (13 papers, 2011 to 2025). A malignant tumor that arises from hepatocytes. "In this work, we first established the ATP7B R778L mutant human hepatocellular carcinoma HepG2 cell line and analyzed the effect of this mutation on the ATP7B protein." (PMID 37717021, 2023). "A later study suggested copper-induced autophagy as a survival mechanism to prevent cell death in human hepatocellular carcinoma HepG2 cells deficient of ATP7B (HepG2 ATP7B−/−)." (PMID 34831341, 2021). "In this study, we have characterized a polarized human hepatoma cell line that lacks ATP7B due to a targeted knockout mutation." (PMID 24892424, 2014). "As ATP7B overexpression was implicated to confer resistance, the question was addressed whether retroviral vectors overexpressing ATP7B can confer improved Cp resistance in hepatoma cell lines." (PMID 29416650, 2018). "We re-addressed the role of ATP7B in hepatocytes and characterized transporter expression after establishment of Cp resistant hepatoma cells." (PMID 29416650, 2018). "In this report, we took advantage of a human hepatoma cell line that carries a knockout (KO) of ATP7B." (PMID 29416650, 2018). "Human hepatoma cell lines are excellent cellular platforms to study ATP7B and its role in Cu homeostasis as exemplified by the most widely studied hepatic cell line, HepG2." (PMID 24892424, 2014). "A targeted knockout of ATP7B (KO) was established in the most widely used human hepatoma cell line, HepG2 for molecular studies of the pathogenesis and treatment of the disease." (PMID 24892424, 2014). "Long-Evans Cinnamon (LEC) rats harbor a deletion in the ATP7B gene, accumulate large amounts of copper in the liver, and develop chronic hepatitis, which eventually leads to hepatocellular carcinoma." (PMID 21838703, 2012). "Whereas we previously demonstrated that COMMD1 expression augments the protein degradation of ATP7B in vitro, others have shown a decline in Atp7b expression after depletion of Commd1 in the mouse hepatoma Hepa1-6 cells." (PMID 22216203, 2011). "Furthermore, autophagy was induced in normal human hepatocellular carcinoma cells (HepG2) leading to enhanced colocalization of ATP7B and LC3B on the autophagosome membranes." (PMID 34831341, 2021). "We generated a stable human hepatoma ATP7B KO cell line to study Cu metabolism." (PMID 24892424, 2014). "Our results that were derived in isogenic sublines of a human hepatoma cell line, either after native expression, gene knockout or overexpression, suggest that ATP7B does not affect Cp sensitivity." (PMID 29416650, 2018). "In heterologous or hepatoma-derived cell lines, overexpressed ATP7B-H1069Q is strongly retained in the ER and fails to move to the post-Golgi sites, resulting in toxic copper accumulation." (PMID 29674751, 2018). "(i) ATP7B does not have an impact on Cp-induced toxicity, at least for hepatoma cells which represent the primary physiological expression site of this transporter." (PMID 29416650, 2018). "In order to explore an establishment of Cp resistance in the absence of ATP7B, we used a previously generated hepatoma KO cell line." (PMID 29416650, 2018). "In order to re-evaluate the impact of ATP7B for establishment of Cp resistance, a recently generated human hepatoma HepG2 cell line lacking functional ATP7B (KO) was compared to parental cell line expressing high levels of ATP7B." (PMID 29416650, 2018). "Having shown that ATP7B expression does not modulate Cp sensitivity and accumulation in hepatoma cells, the question was addressed which other genes may result in an adaptation to toxic Cp concentrations." (PMID 29416650, 2018).
Alzheimer disease (11 papers, 2011 to 2025). A progressive, neurodegenerative disease characterized by loss of function and death of nerve cells in several areas of the brain leading to loss of cognitive function such as memory and language. "That copper metabolism is involved in the pathogenesis of Alzheimer’s disease is however, emphasized as several polymorphisms in the gene encoding the copper transporter ATP7B seem to be linked to the development of Alzheimer’s disease." (PMID 23055972, 2012). "Several single nucleotide polymorphisms (SNPs) in the ATP7B gene have been shown to increase the relative risk of developing Alzheimer’s disease by up to 82%." (PMID 23055972, 2012). "In parallel, transcriptomic analysis revealed that microglia from IGF-1RKO−tdTomato mice increased expression of Aspm, a positive regulator of the cell cycle and Atp7b, a gene involved in cellular activation during Alzheimer ́s disease." (PMID 36890580, 2023).
glioma (8 papers, 2016 to 2025). A benign or malignant brain and spinal cord tumor that arises from glial cells (astrocytes, oligodendrocytes, ependymal cells). "In conclusion, the results suggest that the expression patterns and clinical significance of ATP7A and ATP7B in glioma differ: high ATP7A expression is associated with poor prognosis, while ATP7B downregulation also predicts poor clinical outcomes." (PMID 41463095, 2025). "Furthermore, the expression patterns of ATP7A and ATP7B significantly affect the prognosis of glioma: high expression of ATP7A is associated with poor clinical prognosis, while low expression of ATP7B is also associated with poor prognosis." (PMID 41463095, 2025). "High expression of ATP7B was found to be associated with decreased survival in patients with colorectal and lung squamous cell carcinomas and increased survival in those with renal clear cell carcinoma, low-grade glioma, and thyroid cancer." (PMID 40316883, 2025). "According to a recent study, ATP7B is differentially expressed in various carcinomas, suggesting a prognostic implication for patients with low-grade glioma and renal clear cell carcinoma." (PMID 40316883, 2025). "In contrast, ATP7B expression in glioma tissues was significantly lower than in normal brain tissues (p < 0.05)." (PMID 41463095, 2025). "Although ATP7B is underexpressed in glioma tissues, and patients with low ATP7B expression have a lower survival rate, its role in copper ion homeostasis is limited." (PMID 41463095, 2025). "In our study, ATP7B expression in gliomas was higher than in normal tissues, and it was significantly higher in high-grade gliomas than in low-grade gliomas." (PMID 38037104, 2023). "In different databases, the evaluation of the prognostic value of ATP7B in glioma patients was inconsistent, indicating that ATP7B had greater research space and was more worthy of study." (PMID 38037104, 2023). "Only GLS and ATP7B had low expression levels in glioma patients; however, others, including FDX1, LIPT1, DLD, and SLC31A1, were overexpressed." (PMID 37515314, 2023). "Compared with normal group, the expression of ATP7B was up-regulated in glioma group, and the up-regulation was more obvious in high-grade gliomas than in low-grade gliomas." (PMID 38037104, 2023). "Our result showed that the high expression level of SLC31A1 and low expression of ATP7B were found in more aggressive gliomas, which indicate high influx and low efflux of copper, resulting in copper retention in these tumors." (PMID 36267281, 2022). "The results of IHC revealed that the expression level of SLC31A1 in high-grade glioma was significantly higher than in low-grade glioma, and ATP7B was lower in high-grade glioma, which was in line with the results from sequencing." (PMID 36267281, 2022). "Furthermore, Cox regression analysis in the TCGA database showed that FDX1, LIPT1, DLD, DLAT, SLC31A1, ATP7A, and DLST might be risk factors; however, LIAS, ATP7B, and GCSH were significant preventive factors for gliomas." (PMID 37515314, 2023). "The expression of GLS (p < 0.001), LIPT1, FDX1, SLC31A1 (p < 0.01), DLST, CDKN2A, PDHA1, ATP7A, ATP7B, and NFE2L2 (p < 0.05) was different between glioma and adjacent tissues." (PMID 36936439, 2023).
colorectal cancer (7 papers, 2022 to 2025). A primary or metastatic malignant neoplasm that affects the colon or rectum. "The copper efflux transporter encoded by the ATP7B gene is highly expressed in colorectal cancer, and its elevated expression level is significantly correlated with poor prognosis in colorectal cancer patients receiving oxaliplatin-based chemotherapy." (PMID 40276654, 2025). "Following CDKN2A knockout, we detected an upregulation of the copper uptake gene SLC31A2 and a downregulation of the copper efflux gene ATP7B in colorectal cancer cell lines." (PMID 38888512, 2024). "Dysregulation of SLC31A1, ATP7B, and ATP7A has been implicated in colorectal cancer and can affect copper homeostasis and tumor growth." (PMID 38898987, 2024). "The study revealed that, compared to normal tissues, genes FDX1, DLD, DBT, DLST, and DLAT were significantly downregulated in colorectal cancer tissues, while LIPT1, GCSH, and ATP7B genes were upregulated." (PMID 40276654, 2025). "Patients with low ATP7B mRNA expression levels in colorectal cancer have better PFS and optimal curative effects from oxaliplatin plus 5-fluorouracil treatment compared to those with high ATP7B mRNA expression." (PMID 38727322, 2024). "In one clinical trial looking at ATP7A and ATP7B expression levels in colorectal cancer patients treated with first line OXP, patients with lower levels of ATP7B demonstrated better overall survival." (PMID 36499737, 2022). "It was found that the mutation frequency of each regulator is relatively low, of which ATP7A showed the highest mutation rate, followed by ATP7B and LIPT1, while FDX1, CDKN2A, SLC31A1, and GCSH showed no mutation in all colorectal cancer tissues." (PMID 36248908, 2022).
liver failure (7 papers, 2016 to 2025). A liver disease characterized by the liver losing or has lost all of its function. "Case presentation: We report the case of a 19-year-old woman with WD presenting with liver failure, skin manifestations, and acute neurovisceral symptoms.The rare mutation in intron 1 of ATP7B (c.51+2T > G) was further confirmed by gene sequencing." (PMID 34381801, 2021). "We have suggested that this mutation in the ATP7B gene might contribute to liver findings, progressing to liver failure with a loss of function effect." (PMID 33573009, 2021). "The ATP7B gene is mostly expressed in the liver and is responsible for copper transport in hepatocytes; therefore, excess copper ions in WD patients are not eliminated in the liver via bile but instead accumulate in the liver, eventually leading to cirrhosis and even liver failure." (PMID 40002122, 2025).
Dystonia (6 papers, 2020 to 2025). An abnormally increased muscular tone that causes fixed abnormal postures. "In conclusion, we identified four novel mutations in ATP7B gene and found that younger age of onset, the presence of dystonia, and genotype with severe mutations may be predictive of neurological worsening in the neurological WD patients that received chelator therapy." (PMID 35444691, 2022).
Parkinson disease (6 papers, 2011 to 2025). A progressive degenerative disorder of the central nervous system characterized by loss of dopamine producing neurons in the substantia nigra and the presence of Lewy bodies in the substantia nigra and locus coeruleus. "Given the mounting evidence of the possible involvement of single heterozygous ATP7B mutations in phenotypes with parkinsonism, it can be speculated that p.H1069Q mutation in our CBS-NAV patient has led to the subclinical dysregulation of copper metabolism." (PMID 36553628, 2022). "There is limited information about the role of those biomolecules in the pathophysiology of Parkinson's disease; for instance, it is known that CTR1 is decreased in substantia nigra pars compacta in Parkinson's disease and that a mutation in ATP7B could be associated with Parkinson's disease." (PMID 24672633, 2014). "Ceruloplasmin activity is decreased in Parkinson's disease; to our knowledge, there are no studies that show or refute any relationship between ATP7B dysfunction and decreased ceruloplasmin activity in Parkinson's disease." (PMID 24672633, 2014). "A specific role for these two transporters in Parkinson's disease has not been thoroughly investigated, but there is at least one study that relates ATP7B to Parkinson's disease to some extent." (PMID 24672633, 2014).